C8G (complement C8 gamma chain)
Description:
Component of the membrane attack complex (MAC), a multiprotein complex activated by the complement cascade, which inserts into a target cell membrane and forms a pore, leading to target cell membrane rupture and cell lysis. The MAC is initiated by proteolytic cleavage of C5 into complement C5b in response to the classical, alternative, lectin and GZMK complement pathways. The complement pathways consist in a cascade of proteins that leads to phagocytosis and breakdown of pathogens and signaling that strengthens the adaptive immune system. C8G, together with C8A and C8B, inserts into the target membrane, but does not form pores by itself. During MAC assembly, associates with C5b, C6 and C7 to form the C5b8 intermediate complex that inserts into the target membrane and traverses the bilayer increasing membrane rigidity.
Synonyms: C8C
Tractability: Small molecule: it has a high-quality binding pocket. Antibody: UniProt places it where antibodies can reach, with high confidence; its Gene Ontology location is reachable by antibodies, with high confidence; UniProt predicts a signal peptide or a membrane-spanning region. PROTAC: its protein half-life has been measured.
Gene: Protein-coding gene on chromosome 9 (136,944,870 to 136,946,980, forward strand). Ensembl gene ENSG00000176919.
Subcellular location: Secreted; Target cell membrane
Pathways (Reactome):
Immune System: Regulation of Complement cascade; Terminal pathway of complement
Gene Ontology:
Molecular function: protein binding; wide pore channel activity
Biological process: complement activation; complement activation, GZMK pathway; killing of cells of another organism; positive regulation of immune response; transmembrane transport
Cellular component: blood microparticle; extracellular exosome; extracellular region; membrane attack complex; other organism cell membrane; plasma membrane
Genetic constraint (gnomAD): Loss-of-function variants: 40 observed, 28.35 expected, observed/expected ratio (o/e) 1.41, 90% interval 1.09 to 1.81. The synonymous counts are far from expectation, so gnomAD's model fits this gene poorly and the ratio says little. Missense variants: 300 observed, 250.76 expected, observed/expected ratio (o/e) 1.2, 90% interval 1.09 to 1.32. Synonymous variants: 158 observed, 107 expected, observed/expected ratio (o/e) 1.48, 90% interval 1.3 to 1.68.
Homologues: Orthologues: chimpanzee C8G (99% identical), macaque C8G (95% identical), pig C8G (82% identical), dog C8G (77% identical), rat C8g (76% identical), mouse C8g (74% identical), guinea pig C8G (73% identical), tropical clawed frog C8G (36% identical), zebrafish c8g (32% identical).
Diseases named in the same sentence as C8G in open-access papers:
C8G is named in the same sentence as 17 diseases in open-access papers, as found by Europe PMC text mining. Sharing a sentence is not in itself a finding about the gene and the disease. The quoted sentences say what the papers report.
COVID-19 (4 papers, 2022 to 2025). A disease caused by infection with severe acute respiratory syndrome coronavirus 2. "In the complement pathway, IVIG treatment decreased levels of C1RL, C8G, and CFD compared to COVID-19 controls." (PMID 40821834, 2025). "However, radar plots revealed a clear decrease in the average abundance of several complement proteins in IVIG-treated patients compared to both COVID-19 controls and healthy donors, including C1RL, CFD, CD5L, C8G, and CFHR5." (PMID 40821834, 2025). "Interestingly, when comparing AH in the RO group transplanted with GTKO porcine cornea with that in the survival group, six proteins (C3, C5, C7, C9, C8B, and C8G) were enriched in the “Coronavirus disease - COVID-19” KEGG pathway (data not shown)." (PMID 35401527, 2022).
Amoebiasis (2 papers, 2024).
babesiosis (1 paper, 2023). Babesiosis refers to a condition caused by microscopic parasites that infect the red blood cells. "Other identified proteins that differentiated uncomplicated from complicated babesiosis were various complement cascade components (CFI, CFP, C2, SERPING1, C8G), extracellular matrix components (TGFBI), acute phase proteins (ORM1, ITIH2, ITIH4, FGA, TF, RBP4) and lipoproteins (apoE)." (PMID 37353646, 2023).
breast carcinoma (1 paper, 2024). "We identified seven potential genes within breast cancer: NOL4, STAR, C8G, NEIL1, SLC46A3, FRMD6, and SCARF2." (PMID 39199284, 2024). "Through differential expression analysis and mutual information, we identified seven genes (NOL4, STAR, C8G, NEIL1, SLC46A3, FRMD6, and SCARF2) that are potential biomarkers in breast cancer." (PMID 39199284, 2024). "C8G (complement C8 gamma chain) facilitates membrane attack complex (MAC) formation and cell lysis and is down-regulated in breast cancer, suggesting the suppression of cell lysis." (PMID 39199284, 2024).
cataract (1 paper, 2023). Partial or complete opacity of the crystalline lens of one or both eyes that decreases visual acuity and eventually results in blindness. "Whereas, within the female cohort, two complement proteins (C4B and F2) were upregulated and one (C8G) downregulated in the POAG samples when compared to cataracts." (PMID 37763167, 2023). "Additionally, C8G (FC = 0.78, p = 0.025) exhibited downregulation in the POAG group compared to cataracts." (PMID 37763167, 2023).
Stroke (1 paper, 2020). Sudden impairment of blood flow to a part of the brain due to occlusion or rupture of an artery to the brain. "Specifically, elements of the alternative pathway of complement system and MAC proteins, i.e., CFI, C6, C8A, C8G, C9 were found to be activated but also undergoing regulation at 3 months post-stroke." (PMID 32849183, 2020).
tumor (2 papers, 2021 to 2022). "The amplification of genes such as COL5A1, IDO1, and GOLIM4 were in accordance with their higher expression in tumor samples, whereas no significant change of protein or phosphorylation levels was observed for genes with genomic amplification, such as CD4, CD7, LIME1, UNC93B1, C1S, C1R, or C8G." (PMID 34400640, 2021).
infection (1 paper, 2019). The state of being infected such as from the introduction of a foreign agent such as serum, vaccine, antigenic substance or organism. "As for CBA/Ca, Cfb, a protein of the alternative pathway, is upregulated under infection when compared to its counterpart control, together with C8g, C3 and Cfh." (PMID 31412915, 2019).
inflammation (1 paper, 2021). Aberrant reaction of the microcirculation characterized by movement of fluid and leukocytes from the blood into extravascular tissues. "Therefore, C8G expression in perivascular astrocytes may be induced by inflammatory mediators released from ECs, to protect the brain against cerebral vascular inflammation." (PMID 34149451, 2021).
C8G also shares sentences with these, for which no sentence is quoted: cancer (1 paper); colon adenocarcinoma (1); E. coli infection (1); glomerulosclerosis (1); Obesity (1); renal fibrosis (1); staphylococcus aureus infection (1); thyrotoxicosis (1).